SPICE1-CFAP44 (SPICE1-CFAP44 readthrough (NMD candidate))
Gene: Protein-coding gene on chromosome 3 (113,361,901 to 113,515,151, reverse strand). Ensembl gene ENSG00000285943.
Genetic constraint (gnomAD): Missense variants: 908 observed, 989.85 expected, observed/expected ratio (o/e) 0.92, 90% interval 0.87 to 0.97. Synonymous variants: 291 observed, 344.99 expected, observed/expected ratio (o/e) 0.84, 90% interval 0.77 to 0.93.